ANGPT4 (angiopoietin 4)
Description:
Binds to TEK/TIE2, modulating ANGPT1 signaling. Can induce tyrosine phosphorylation of TEK/TIE2. Promotes endothelial cell survival, migration and angiogenesis.
Synonyms: ANG3; ANG4
Tractability: Antibody: UniProt places it where antibodies can reach, with high confidence; its Gene Ontology location is reachable by antibodies, with high confidence; UniProt predicts a signal peptide or a membrane-spanning region.
Gene: Protein-coding gene on chromosome 20 (869,900 to 916,334, reverse strand). Ensembl gene ENSG00000101280.
Subcellular location: Secreted
Pathways (Reactome):
Hemostasis: Tie2 Signaling
Gene Ontology:
Molecular function: receptor tyrosine kinase binding; transmembrane receptor protein tyrosine kinase activator activity
Biological process: cellular response to hypoxia; endothelial cell proliferation; negative regulation of angiogenesis; negative regulation of apoptotic process; negative regulation of blood vessel endothelial cell migration; positive regulation of angiogenesis; positive regulation of blood vessel endothelial cell migration; positive regulation of endothelial cell migration; positive regulation of peptidyl-tyrosine phosphorylation; signal transduction; blood coagulation
Cellular component: extracellular region; extracellular matrix
Genetic constraint (gnomAD): Loss-of-function variants: 50 observed, 53.22 expected, observed/expected ratio (o/e) 0.94, 90% interval 0.75 to 1.19. The upper end of that interval is the gene's LOEUF score, 1.19, which puts it in group 5 of 6, group 1 being the genes least tolerant of losing a copy. Missense variants: 648 observed, 649.4 expected, observed/expected ratio (o/e) 1, 90% interval 0.94 to 1.07. Synonymous variants: 251 observed, 260.45 expected, observed/expected ratio (o/e) 0.96, 90% interval 0.87 to 1.07.
Homologues: Orthologues: chimpanzee ANGPT4 (99% identical), macaque ANGPT4 (95% identical), pig ANGPT4 (69% identical), dog ANGPT4 (68% identical), rabbit ANGPT4 (60% identical), mouse Angpt4 (55% identical), rat Angpt4 (55% identical), zebrafish angpt4 (46% identical). Paralogues in human: ANGPT1 (44% identical), ANGPT2 (44% identical), ANGPTL6 (26% identical), TNC (26% identical), TNXB (26% identical), ANGPTL2 (25% identical), FIBCD1 (25% identical), ANGPTL1 (25% identical), ANGPTL7 (24% identical), TNR (24% identical), FGB (21% identical), TNN (21% identical), and 13 more.
Diseases named in the same sentence as ANGPT4 in open-access papers:
ANGPT4 is named in the same sentence as 42 diseases in open-access papers, as found by Europe PMC text mining. Sharing a sentence is not in itself a finding about the gene and the disease. The quoted sentences say what the papers report.
glioblastoma (5 papers, 2011 to 2021). The most malignant astrocytic tumor (WHO grade IV). "Angiopoietin-4 is involved in glioblastoma progression by enhancing tumor angiogenesis and cell viability." (PMID 29849945, 2018). "Angiogenic effects of ANGPT4 have also been observed in glioblastoma." (PMID 24391823, 2013). "Previous studies have revealed that angiopoietin 4 and VEGF were expressed at higher levels during hypoxia in U87 glioblastoma cells." (PMID 31395030, 2019).
ovarian carcinoma (3 papers, 2020 to 2022). A malignant neoplasm originating from the surface ovarian epithelium. "The upregulation of ANGPT found in our RNASeq analysis is consistent with studies using mouse models wherein an increased expression of angiopoietins (ANGPT1, ANGPT2, and ANGPT4 and TIE2 (angiopoietin receptor) have been shown to promote ovarian cancer progression." (PMID 35052372, 2021).
glioma (2 papers, 2018 to 2023). A benign or malignant brain and spinal cord tumor that arises from glial cells (astrocytes, oligodendrocytes, ependymal cells). "Furthermore, EGFRvIII induces glioma angiogenesis by Myc-dependent transcriptional activation of angiopoietin-4 (ANG4) (see Crosstalk between Myc-Dependent Angiogenesis and Metabolism in GBM below)." (PMID 36835628, 2023).
acute respiratory distress syndrome (1 paper, 2024). Progressive and life-threatening pulmonary distress in the absence of an underlying pulmonary condition, usually following major trauma or surgery. "Significant variation within the ANGPT4 (angiopoietin 4) gene on Chr20 was also indicated to be associated with resistance to AI, with increased levels of ANGPT4 previously shown to be related to acute respiratory distress syndrome and severity of SARS-CoV-2 infection in humans." (PMID 39337540, 2024).
Alzheimer disease (1 paper, 2017). A progressive, neurodegenerative disease characterized by loss of function and death of nerve cells in several areas of the brain leading to loss of cognitive function such as memory and language. "ANGPT4 has been related to Alzheimer’s disease and vascular dementia." (PMID 28923014, 2017).
diabetes (1 paper, 2018). "In mouse, excess of exogenous Angpt4 or ANGPT4 similarly induced blood and lymphatic vascular remodeling and ANGPT4 improved vascular function in streptozotocin-induced model for diabetes, suggesting that Angpt4, ANGPT4 and Angpt1 have similar functions." (PMID 30444491, 2018).
glaucoma (1 paper, 2022). Increased pressure in the eyeball due to obstruction of the outflow of aqueous humor. "Based on the defects in the SC morphology, we next investigated whether Angpt2−/− and Angpt2−/−;Angpt4−/− mice have glaucoma-associated functional defects as well." (PMID 36190459, 2022). "Collectively, these data showed that Angpt2−/−;Angpt4−/− mice exhibit a glaucoma-like phenotype." (PMID 36190459, 2022). "Despite the reduction in SC area, aged Angpt2+/−;Angpt4−/− mice did not display major signs of glaucoma, possibly owing to their less convoluted and thus less obstructive SC morphology when compared to full Angpt2 deletion mice." (PMID 36190459, 2022).
heart injuries (1 paper, 2023). "Our study provides a mechanistic understanding of heart regeneration at single-cell precision, identifies Angpt4 as a key regulator of cardiomyocyte proliferation and regeneration, and offers a novel therapeutic target for improved recovery after human heart injuries." (PMID 37155312, 2023).
lung disease (1 paper, 2021). "The present review focuses on the clinical impact of the Angiopoietin-1, Angiopoietin-2, and Angiopoietin-4 levels in patients diagnosed with NSCLC, emphasizing the interaction between them, and how they affect the development, progression, and metastasis of lung disease." (PMID 34833409, 2021).
myocardial infarction (1 paper, 2023). Gross necrosis of the myocardium, as a result of interruption of the blood supply to the area, as in coronary thrombosis. "Furthermore, we found that ANGPT4 could enhance proliferation of neonatal rat cardiomyocytes, and promote cardiac repair in mice after myocardial infarction, indicating that the function of Angpt4 is conserved in mammals." (PMID 37155312, 2023).
polydactyly (1 paper, 2024). A disease characterized by the presence of polydactyly, including syndromic and non-syndromic forms. "1172T>C) of the ANGPT4 gene were associated with polydactyly." (PMID 38612286, 2024). "Combined with the results of genome-wide association studies, we identified candidate genes associated with the crest (SMYD and STOX2) and polydactyly (SLC52A3 and ANGPT4)." (PMID 38612286, 2024). "SLC52A3 and ANGPT4 genes might play an important role in the formation of the polydactyly of the Taihu Dianzi pigeon." (PMID 38612286, 2024). "A total of 151 SNP loci significantly correlated with the polydactyly trait were identified through GWAS, and five genes, R-spondin 4 (RSPO4), tensin-3 (TNS3), chloride channel 7 (CLCN7), SLC52A3, and ANGPT4, were annotated to be significantly correlated with polydactyly." (PMID 38612286, 2024). "Furthermore, three genes affecting the development of polydactyly, angiopoietin 4 (ANGPT4), histocompatibility minor 13 (Hm13), and solute carrier family 52 member 3 (SLC52A3), were identified by overlap analysis." (PMID 38612286, 2024).
retinal degeneration (1 paper, 2018). Degeneration of the retina. "In hyperoxia, which in short-term promotes astrocyte differentiation, in long-term causes retinal degeneration and paradoxically can cause hypoxia by blocking vascular development in the retina, Angpt1 mRNA expression was decreased while Angpt2 and Angpt4 mRNA levels increased." (PMID 30444491, 2018).
tick-borne diseases (1 paper, 2022). "4-HNE, generated during tick-borne diseases, also binds to other metabolically important proteins, including GSH transferase, ANGPT4, clathrin, PDIA3, actinin-4, and PRDX5." (PMID 35457192, 2022).
Venous malformation (1 paper, 2018). A vascular malformation resulting from a developmental error of venous tissue composed of dysmorphic channels lined by flattened endothelium and exhibiting slow turnover. "Moreover, based on reported venous-specific effects of inducible Tie2 deletion in retina and over-activating TIE2 mutations in venous malformations, Tie2 signaling appears particularly important to venous development that may contribute to the vessel-type-specific phenotype in Angpt4-/- mice." (PMID 30444491, 2018).
tumor (20 papers, 2009 to 2026). "Angiopoietin-4 (Ang-4) and Angiopoietin-3 (Ang-3) seem to act as agonists of the Tie-2 receptor, while their role in tumor angiogenesis and invasion is unclear." (PMID 34833409, 2021). "These include some examples of genes that were hypo-methylated and up-regulated during the transition from KSHV (+) cell to KSHV (+) tumor and are now hyper-methylated and down-regulated, such as Angpt4, Pdgfb, and Shank3." (PMID 32603362, 2020). "In mouse tumor transplantation studies, exogenous Angpt4 has been reported to either inhibit or promote tumor growth, and similarly to Angpt2, Angpt4 expression has been reported to increase in hypoxia." (PMID 30444491, 2018). "Notably, genes implicated in oncogenic signaling and tumor progression, including GNB4, EGF, MYB, IL6R, ANGPT4, and ITGB8, were consistently downregulated in both BxPC3 and SW1990 cells following PCDH1 silencing." (PMID 41602375, 2026). "Angiopoietins, including ANGPT1, ANGPT2, and ANGPT4, have been reported to act as ligands of the tyrosine kinase receptors TIE1 and TIE2 to activate MAPK signaling pathways during tumor angiogenesis in mammals." (PMID 37155312, 2023).
cancer (7 papers, 2011 to 2024). A tumor composed of atypical neoplastic, often pleomorphic cells that invade other tissues. "Furthermore, there is still some controversy in the literature, related to the role of ghrelin, ANGPT4, HIF-1, and TNF-α in cancer cachexia and metastasis development, indicating the necessity of more studies." (PMID 26508818, 2015).
bacterial infections (3 papers, 2022 to 2024). "Angiopoietin 4 (ANGP4), CD9, and immunoglobulin E (IgE) were increased and LFA3, IL5, and CD45RB were among the most decreased proteins in bacterial infection." (PMID 37831367, 2024).
cardiac disease (1 paper, 2023). "Nevertheless, the application of Angpt4 in the therapy of human cardiac disease needs further validation and careful safety assessment." (PMID 37155312, 2023). "The essential and conserved function of Angpt4 as well as the novel mechanisms involving cellular coordination may shed light on treatments of human heart disease." (PMID 37155312, 2023).
retinopathy (1 paper, 2018). "Pathophysiological relevance of Angpt4 deficiency was evaluated in oxygen-induced retinopathy (OIR) model and using histopathological and ultrastructural analysis of postnatal and aged mice." (PMID 30444491, 2018). "Angpt4 deficiency did not affect capillaries or arteries either in physiological development, during aging or in retinopathy in OIR model, indicating a venous-specific function." (PMID 30444491, 2018).
ANGPT4 also shares sentences with these, for which no sentence is quoted: infection (10 papers); colitis (5); lung carcinoma (2); prostate carcinoma (2); cardiovascular disease (1); Chronic colitis (1); colon carcinoma (1); colorectal cancer (1); diabetic retinopathy (1); endometriosis (1); helminth infection (1); hepatocellular carcinoma (1); intestinal diseases (1); intestinal infections (1); liver cancer (1); Obesity (1); pancreatic cancer (1); pancreatitis (1); retinal ischemia (1); serous carcinoma (1); Stroke (1); vascular dementia (1); vascular tumors (1).